LRCOL1 (leucine rich colipase like 1)
Tractability: Antibody: UniProt predicts a signal peptide or a membrane-spanning region; its Gene Ontology location is reachable by antibodies, with medium confidence.
Gene: Protein-coding gene on chromosome 12 (132,603,150 to 132,610,582, reverse strand). Ensembl gene ENSG00000204583.
Gene Ontology:
Molecular function: enzyme activator activity
Biological process: digestion; lipid catabolic process
Cellular component: extracellular region
Genetic constraint (gnomAD): Loss-of-function variants: 20 observed, 19.79 expected, observed/expected ratio (o/e) 1.01, 90% interval 0.71 to 1.47. The upper end of that interval is the gene's LOEUF score, 1.47, which puts it in group 6 of 6, group 1 being the genes least tolerant of losing a copy. Missense variants: 198 observed, 194.34 expected, observed/expected ratio (o/e) 1.02, 90% interval 0.91 to 1.15. Synonymous variants: 96 observed, 81.01 expected, observed/expected ratio (o/e) 1.18, 90% interval 1 to 1.4.
Homologues: Orthologues: chimpanzee LRCOL1 (98% identical), macaque LRCOL1 (84% identical), guinea pig LRCOL1 (53% identical), rat Lrcol1 (51% identical), mouse Lrcol1 (47% identical). Paralogues in human: CLPS (15% identical), CLPSL2 (14% identical), CLPSL1 (10% identical).
Diseases named in the same sentence as LRCOL1 in open-access papers:
LRCOL1 is named in the same sentence as 1 disease in open-access papers, as found by Europe PMC text mining. Sharing a sentence is not in itself a finding about the gene and the disease.
LRCOL1 shares sentences with these, for which no sentence is quoted: psychiatric disorder (1 paper).